CD4 (CD4 molecule)
Diseases named in the same sentence as CD4 in open-access papers (continued):
Sharing a sentence is not in itself a finding about the gene and the disease.
tumor (continued). "Furthermore, a fraction of both CD4+ T cell and CD8+ T cells recruited to the tumor microenvironment have lower CD5 levels than T cells in lymph and spleen, either because CD5 is downregulated by the tumor microenvironment or T cells with lower CD5 are preferentially infiltrated into tumors." (PMID 33584650, 2020). "Single cell suspension from fresh OSCC tumour tissue (n = 24), sentinel nodes (n = 25), non-sentinel nodes (n = 42) and blood (n = 26) was analyzed by flow cytometry to determine expression of activation surface markers on CD4 and CD8 T cells." (PMID 33339891, 2020). "Interestingly, CSF1/CSFR1 blockade achieved up to 85% tumor regression in a murine model when combined with PD1/CTLA4 inhibitors and gemcitabine, improved tumor regression in this murine model as well as increased effector CD8+ and CD4+ TIL infiltration and activity." (PMID 32823814, 2020). "Moreover, both CD4+ and CD8+ CARMSLNz T cells started to express PD-L1 and kept its expression for 40 h after co-cultured with H460-MSLNGL tumor cells." (PMID 32514352, 2020). "In addition, under the anti-PD-1 treatment in addition to the anti-VEGFR-2, CD4+ T cells in HCC normalized vessel formation, which might be helpful for the anti-tumor effect of this regimen." (PMID 33379384, 2020). "In addition, when cancer cells transfer to an abnormal environment, CD4+ T and CD8+ T cells may help tumor cells escape immune surveillance." (PMID 32377504, 2020). "Interestingly, in both primary and distant tumours, the infiltration levels of CD3+, CD4+ and CD8+ T cells were substantially higher in the BP plus aCD47 combination treatment group than in the control groups, revealing the adaptive immunological responses triggered in distant metastases as well." (PMID 33014356, 2020). "Furthermore, there was an increase in the Tregs subset (CD3+CD45+CD4+CD25+Foxp3+) in the cisplatin (∗∗∗P < 0.001 vs. T), moxibustion (∗∗P < 0.01 vs. T), and combinatorial therapy (∗∗P < 0.01 vs. T) groups compared with that in the untreated tumor-bearing mice." (PMID 33456484, 2020). "In our data, though the mechanism is not disclosed, CD4+ cells in tumour tended to increase." (PMID 31914969, 2020). "Besides, multiple infiltrating T cells, including CD8+ T cells (CD3+ and CD8+), T helper cells (CD3+, CD4+, and CD25−), and regulatory T cells (CD3+, CD4+, and CD25 high) were collected, suggesting that our characterization of tumor-infiltrating T cells was relatively comprehensive." (PMID 33584715, 2020). "Furthermore, it was suggested that tumor SDC-1 downregulation facilitates ex vivo polarization of CD4+ Th17 and Treg cells of non-inflammatory BC, possibly through increased expression of IL-23 and DLL4." (PMID 32847060, 2020). "Interestingly, depletion of CD4+ T cells, but not CD8+ T cells, restored tumor growth in C3-deficient mice." (PMID 32733461, 2020). "While NK cells, CD4+ and CD8+ T cells, dendritic cells (DC) and pro-inflammatory M1 macrophages promote anti-tumor immune responses, heterogeneous populations of myeloid-derived suppressor cells (MDSC), FOXP3+ regulatory T cells and M2 macrophages counteract tumor immunity." (PMID 32987799, 2020). "Interestingly, we could not detect any significant, iron- or cancer therapy-dependent differences in the numbers of CD3+, CD4+ and CD8+ tumor infiltrating lymphocytes per mm3 tumor." (PMID 33344239, 2020). "Still, more significant tumor growth was found in the latter, suggesting that CD8+ T cells take the most important role in the production of antitumor immunity induced by NDV-MIP3α and that CD4+ cells are partially related to the production of antitumor immunity." (PMID 32759233, 2020). "Here, we quantified the proportion of tumor-reactive T cells across multiple cancer types, and observed that although tumor-reactive CD8+ and CD4+ T cells could be identified in most samples across cohorts, the proportion was on average remarkably low (especially for non-MM tumors)." (PMID 33198174, 2020).
tumor (continued). "IHC confirmed elevated CD4+ cells in the non-necrotic areas of tumours from females." (PMID 32451467, 2020). "However, the observation of the highly significant rise in the CD8+ infiltrate and their ability to produce IFN-γ in irradiated T1 tumors is independent of the reduction in tumor size, as is the proportional rise in CD4 Tregs." (PMID 32197352, 2020). "Furthermore, both CD4+ and CD8+ T cells were required for αCTLA-4-mediated MCA205 tumor control." (PMID 31924474, 2020). "Notably, CD3+, CD4, and CD8+ TILs were shown to secret pro-inflammatory cytokines and suppress tumor growth, whereas cancer cells were found to produce CCL18, which increases migration of regulatory T cells to tumor sites and promotes tumor progression." (PMID 32455995, 2020). "However, these cDC2s failed to unleash productive anti-tumor CD4+ T cells, but their functionality was restored following the depletion of Treg cells." (PMID 32674488, 2020). "Indeed, while anti-PD-1 mainly induced the expansion of specific tumor-infiltrating exhausted-like CD8+ T cell subsets, anti-CTLA-4 led to the expansion of an ICOS+ Th1-like CD4+ effector subsets other than engaging specific subsets of exhausted-like CD8 T cells." (PMID 32265933, 2020). "In addition to inducing CD4+ T and CD8+ T cell as well as NK cell-mediated responses, DC-derived antigen-loaded sEVs can induce B cell activation and IgG secretion which play an important helper role in activation of adaptive anti-tumor T cell responses." (PMID 32765528, 2020). "However, there is still a lack of CD4+CD25+ T cells TCR β CDR3 repertoires between tumor tissue and the circulatory immune system." (PMID 33029539, 2020). "Furthermore, the HSPG syndecan-1 was shown to exert an immunomodulatory role on the polarization of CD4+ T helper (Th) subsets isolated from the tumor tissues of patients with inflammatory BC and non-inflammatory BC." (PMID 32847060, 2020). "The lack of decrease in number of tumor-infiltrating CD4+ T cells could be attributable to increased expression of Cxcl9 that was observed in Siah2−/− tumors, which could increase T cell recruitment, compensating for decreased CD4+ T cells proliferation." (PMID 31911617, 2020). "Similarly, Zuazo-Ibarra found that HPD had a significant correlation with negative baseline highly differentiated CD4 T which reflected weaker potential anti-tumor capacities." (PMID 32727409, 2020). "The infiltration of tumor sites by cytotoxic CD8+ T cells is usually correlated with a favorable clinical prognosis, however immunosuppressive conditions can polarize these cells to CD8+FOXP3+ regulatory cells with similar immunomodulatory and angiogenic properties as CD4+ Tregs." (PMID 33343570, 2020). "CIBERSORT was used to analyse the infiltration of SKCM by CD8‐positive and CD4‐positive T cells, DCs, B cells, macrophages, MCs, and NK cells and establish the relationship between chemokines and their receptors in the LN tissues of SKCM patients and the fraction of the immune cells in the tumour." (PMID 31983065, 2020). "CD4+ T cells mainly activate innate and acquired immunity, thus it is not surprising that their levels are lower in tumor tissue and peripheral blood of PC patients, as compared to healthy subjects; consistently, their infiltration is correlated with better OS." (PMID 32012917, 2020). "After intratumoral injection, Flt3L- and OX40L-expressing MVAΔC7L induced more CD8+ and CD4+ T cells responding in distant, non-injected tumors, and synergized with anti-PD-L1 antibody in multiple mouse tumor models as compared to heat-inactivated parental MVA." (PMID 32245497, 2020). "Th2 CD4+ T cells produce IL-4, IL-10, and TGF-β, which may boost tumor progression." (PMID 32595757, 2020).
tumor (continued). "As in the tumor tissues, IFNγ, IL-10, IL-17A, and IL-4 were measured and similar to tumor tissues, in vitro culture of T cells were found to have significantly increased levels of IFNγ and IL-17A, with G-CSFR−/− CD4+ T cells, while IL-10 and IL-4 levels were decreased compared to WT." (PMID 33042110, 2020). "Interestingly, CD4+ T cells engineered with the PD1/CD28 fusion construct provided enhanced T-cell help to improve the anti-tumour activity of CD8+ T cells in a pancreatic cancer and non-Hodgkin lymphoma model." (PMID 32708397, 2020). "Analysis of T cell composition within tumor samples in 102 patients with classical HL, where 29% of the tumor samples were positive for LMP1 by immunohistochemistry, demonstrated higher numbers of CD8+ T cells and CD4+/FoxP3+ T regs in samples from EBV-positive tumors." (PMID 33102204, 2020). "In our investigation we were not able to confirm a connection between the amount of CD8+, CD4+ and CD138+ cells, tumor recurrence or stage progression, nor the association between the amount of CD25+ cells and tumor recurrence in patients with NMIBC as described by other authors." (PMID 32484812, 2020). "Using TIMER, we confirmed that SCARF1 expression is absent from tumor cells, as indicated by a negative “purity” correlation (−0.295), and demonstrated a moderate positive correlation with CD4+ T cell infiltration (purity-corrected partial Spearman's rho value = 0.420, p = 3.79e−16)." (PMID 34354939, 2020). "After tumor cell implantation, unlike in WT mice, the spleen of IL-30KO mice lacked the expansion of the CD4+CD25hiFoxp3+ regulatory T (Treg) cell population (IL-30KO mice: 5.64 ± 2.23% versus WT mice: 19.33 ± 5.60% of the total number of CD4+ cells." (PMID 31366386, 2019). "Additionally, PD-1 and PD-L1 blockade significantly increased the CD8+ to Tregs and CD4+ to Tregs ratios within the tumor, while, on the contrary, there was no significant change in the CD8+ or CD4+ to Tregs ratios." (PMID 31681606, 2019). "Furthermore, high expression of CXCR3 protein was closely correlated with the increased recruitment of CD4+, CD8+ tumor infiltrating lymphocytes (TILs), and dendritic cells, which may partly explain the favorable prognosis in GC." (PMID 31240220, 2019). "That is, CD4+ T cell IL-2 production in the presence of SMG E.G7 remained significantly less (p ≤ 0.02) than cytokine production by the T cells activated in the absence of the tumor." (PMID 31602007, 2019). "However, the FoxP3 negative conventional helper CD4 T cells (Tconv)/Treg ratios within the tumor were significantly elevated upon oncolytic VSV‐GP therapy compared to the PBS control group." (PMID 30972741, 2019). "We have also assessed the tumor immune response at various time points following our more conventionally fractionated regimen of CRT and observed that the tumor infiltration of DCs, CD8+ and CD4+ T cells reached a maximum after one week of treatment (data not shown)." (PMID 30646957, 2019). "The tumor-infiltrating lymphocytes (TILs) in the WT → WT mice demonstrated an enhanced percentage of IL-9-producing CD4+ T cells but no increased percentages of IFN-γ- or IL-17A-producing CD4+ T cells or Tregs." (PMID 31266950, 2019). "The main mechanisms that eliminate tumor cells in CRC are gamma IFN and TNF (α and β) producing CD4 + TH1 cells and IL10 secreted by FoxP3+ regulatory T cells by NK or γδ T cells that suppress or downregulate induction and proliferation of effector T cells at the tumor site." (PMID 31303863, 2019). "B cells are particularly important for CD4 T cell priming, and Bregs are important for suppressing CD4 T cell responses, so we hypothesized that MEK inhibition would specifically augment the number of tumor infiltrating CD4 T cells." (PMID 31671149, 2019).
tumor (continued). "Indeed, in our experiments, we confirmed μMT mice with orthotopic tumors had a higher proportion of CD8+ to CD4+ T cells in the spleen, whilst no change in T cell proportions in the tumor itself." (PMID 30972056, 2019). "Interestingly, these TEX cells also are very similar to T cells which have not received CD4+ T cell help, suggesting that the tumor specific CD8+ T cells identified following initial priming by DCs did not see CD4+ T cell help at that time." (PMID 31379821, 2019). "As described in murine tumor tissues, in IL-30NegPC samples, the lack of IL-30 in both cancer and infiltrating leukocytes was associated with a scanty to absent Foxp3+Treg cell content and a distinct TIA-1+CD4+T cell infiltrate." (PMID 31366386, 2019). "Besides providing support to CTLs, CD4+ T cells can also contribute to the anti-tumor immune response independent of CD8+ T cells by acquiring cytotoxic activity and executing a direct anti-tumor effect." (PMID 31130945, 2019). "Also, PD-L1241-265-specific CD4+ T-cell line G1 produced granzyme B against HLA-DR-matched tumor cell lines pretreated with IFN-γ (HSC-4 and Lu65), but not against Sa-3." (PMID 31221178, 2019). "Hence, a coordinated CD4 and CD8 response is necessary for the complete eradication of a tumor." (PMID 30953535, 2019). "Mechanistically, CD8+ T cells, but not CD4+ T cells, were required to achieve tumor regression." (PMID 31779710, 2019). "Not only did we detect high numbers of CD4+ T cells co-expressing both the transcription factors Foxp3 and Tbet in these HPV16-driven tumors but we also found that their numbers are directly related to the number of tumor-infiltrating type 1-oriented (Foxp3-) effector T cells." (PMID 30658697, 2019). "Previously, we showed that administration of the anti-CD4 mAb had strong antitumor effects superior to those elicited by CD25+ Treg depletion or other immune checkpoint mAbs in B16F10, Colon 26, or Lewis lung carcinoma subcutaneous tumor models, which were completely reversed by CD8+ cell depletion." (PMID 31340866, 2019). "Class I (p66) HER2-DC1 vaccine in TUBO bearing mice led to a significant increase in tumor infiltrating CD8+ T cells but not CD4+ T cells, while class II HER2-DC1 vaccine significantly increased both CD4 and CD8+ T cell infiltration compared to untreated controls (p < 0.001)." (PMID 31475002, 2019). "In addition, the enhanced antigen presentation and T cell activation by M1-like TAMs and dendritic cells could possibly further contribute to increased CD4 and CD8 T cell infiltration, activation and ultimate tumor eradication observed in Cav-2 KO mice." (PMID 31831780, 2019). "These cells were used to explore the impact of tumor Sdc-1 silencing on polarization of CD4+ T cells isolated from non-IBC (under direct and indirect co-culture conditions) and IBC patients (under indirect co-culture conditions) towards Th1, Th2, Th17 and Treg subsets." (PMID 31145753, 2019). "However, IL-15 increased tumor cell apoptosis induced by the combination of CD4 and CD8 T cells, implying that IL-15 is not exclusively sensed and active through NK cells." (PMID 30871626, 2019). "To determine whether miR-301a deletion raises Runx3 expression in tumor-infiltrating immune cells, we isolated CD8+ T cells, CD4+ T cells, CD11b+ cells (including monocytes and macrophages), and CD11c+ cells (including dendritic cells), from B16 tumors developed in WT and miR-301a−/− mice." (PMID 31122259, 2019). "The tumor microenvironment is rich in molecules and several possible mechanisms may increase the number of FOXP3+ Tregs, such as driving CD4+ T-helper cells to develop into FOXP3+ Tregs, recruiting existing FOXP3+ Tregs to tumor sites, and inducing the expansion of retained Tregs." (PMID 31852159, 2019). "Moreover, tumor cell-derived DAMPs and antigens could cause enhanced DC activation which then drive the activation of CD4+ and CD8+ T cells infiltrating the tumor tissue thus subverting the immunosuppressive TME." (PMID 31623629, 2019).
tumor (continued). "Naïve CD4+ T (OR: 12.67, 95% CI 2.26–71.18, P = 0.004), memory CD4+ T (OR: 0.17, 95% CI 0.05–0.66, P = 0.010), memory CD8+ T (OR: 0.11, 95% CI 0.01–0.97, P = 0.047), and CD4+ naïve/memory ratio (OR: 8.50, 95% CI 1.90–38.14, P = 0.005) were independent predictors of tumor response to SBRT." (PMID 31080362, 2019). "However, administration of aCSF1, but not aIL34, significantly decreased the number of tumor-resident CD4+ T cells." (PMID 31552020, 2019). "Overall, this study indicates a low frequency of the circulating antitumor Th1 subset in IBC and suggests that tumor Syndecan-1 silencing enhances ex vivo polarization of CD4+ Th17 and Treg cells of non-IBC, whereby Th17 polarization is possibly mediated via upregulation of IL-23 and DLL4." (PMID 31145753, 2019). "Compared with non-responders, responders show a trend to employ lower peripheral CD4+, CD8+, CD25+Foxp3+Treg and Gr-1+CD11b+MDSC cell density, higher CD8+ to Treg ratio, and similar PD-1+ fraction at day 10, which is consistent with the trend within tumour tissue except CD8+ cells." (PMID 30587849, 2019). "To validate whether H3K79me2‐FOXM1 modulates tumor growth via alteration of the TME composition in vivo, we measured T cells from spleen including CD4+, CD8+, and regulatory T cell (Tregs) as well as BMDCs from EPZ‐ or Thiostrepton‐treated TBM by tail vein injections." (PMID 30628173, 2019). "Thus, CD4+ and CD8+ T cells frequently infiltrate GBC tumor tissues, may lead to IFNγ stimulation of tumor cells and thereby, to activation of tumor suppressive STAT1 signaling." (PMID 30886199, 2019). "After antigen recognition, activation, and proliferation, CD4+ cells synthesize and secrete interleukin-2 (IL-2), human interferon-C (IFN-C), and tumor necrosis factor (TNF), which can dissolve and directly kill tumor cells by recognizing and binding antigens on tumors through antigen receptors." (PMID 31781277, 2019). "This may affect the recruitment of immune cells, including the CD103+ DCs or classical type 1 DCs (cDC1s), which excel in priming and cross-presentation of tumor antigens to CD8+ T cells, and CD11b+ DCs or cDC2s, which are more potent at driving CD4+ helper T cell responses." (PMID 31384667, 2019). "In two previous studies, MHC-II expression on tumor cells by immunohistochemistry was found to be predictive for response to anti-PD1 ICB and was hypothesized to represent a subset of tumors that could stimulate CD4+ helper T cell or cytotoxic activity." (PMID 31792460, 2019). "Indeed, NUP214 neoepitope-specific CD4+ T-cells produced IFN-γ specifically against tumor cells, but not against autologous PBMCs." (PMID 31221207, 2019). "These CD4+ ICOS+ T cells produced IFNγ and could recognize tumor antigens." (PMID 31192215, 2019). "Notably, there was no increase in CD4+CD25+FoxP3+ T cells in all studied tissues in tumor-bearing (TBM) mice on SM16 diet." (PMID 31288845, 2019). "Along this line, suppression of anti-tumor T cell immunity by the oncometabolite d-2-hydroxyglutarate has also recently been described in LGG, which may further limit local activation of IDH1R132H-specific CD4 T cells." (PMID 31240524, 2019). "Tumor size pre-NACT (cT-stage) was inversely correlated with the density of total TILs, CD3+ T cells and CD4+ T lymphocytes in the TC; they were highly present at early stages (cT1) and then decreased along with tumor progression (p = 0.004 for total TILs and CD3+ and p = 0.011 for CD4+ T cells)." (PMID 30717704, 2019). "Unexpectedly, tumor-bearing macrophages and cryo-thermal-induced M1 macrophage polarization could promote CD4+ T-cell differentiation into CD4-CTL and Th17, but the effect of cryo-thermal-induced M1 macrophage was much stronger than that of tumor-bearing macrophages." (PMID 30833570, 2019).